ICAM1 (intercellular adhesion molecule 1)
Diseases named in the same sentence as ICAM1 in open-access papers (continued):
Sharing a sentence is not in itself a finding about the gene and the disease.
parasitemia (14 papers, 2011 to 2023). "The selected doses of 10 mg/kg, 20 mg/kg, and 10 mg/kg were studied by evaluating parasitemia, changes in temperature, body weights, organ weights, histopathological features, nitric oxide, cytokines, and ICAM-1 expression." (PMID 36510199, 2022). "It is worth noting that the higher expression level of ICAM-1 was observed in the gills and skin after parasitic infection compared to that of viral and bacterial infections." (PMID 34489953, 2021). "Combined, our results in this study demonstrate that ICAM-1 plays an important role in the mucosal immune response to viral, bacterial, and parasitic infections in teleost fish." (PMID 34489953, 2021). "When compared to the viral and bacterial infections, the higher expression level of ICAM-1 was detected in skin and gills after parasitic infection." (PMID 34489953, 2021). "In contrast, almost all remaining tissues examined herein exhibited an enhanced ICAM-1 expression in response to bacterial and parasitic infections." (PMID 34489953, 2021). "In vivax malaria, urinary GAGs correlated with angiopoietin-2 (r = 0.41, p = 0.003), ADMA (r = 0.40, p = 0.004), and ICAM-1 (r = 0.54, p < 0.0001), with the correlation with ADMA and ICAM-1 remaining significant after adjusting for parasitemia (p = 0.0001)." (PMID 33963210, 2021). "Yet, similar to virus and bacteria, ICAM-1 is also critical for mucosal immune response against parasitic infection in teleost fish." (PMID 34489953, 2021). "Rainbow trout were also challenged with I. multifiliis to detect the differential expression of the ICAM-1 gene in response to parasitic infection." (PMID 34489953, 2021). "Our finding demonstrated increased ICAM-1 expression levels in the tested tissues after parasitic infection." (PMID 34489953, 2021). "Constant human recombinant IFN-α treatment also resulted in enhanced survival, which was associated with an IFN-γ–mediated decrease of parasitemia, expression of intracellular adhesion molecule-1 (ICAM-1 or CD54) in the brain, and CD8+ T cells sequestration." (PMID 33344264, 2020). "Both C57BL/6 and ICAM-1 knockout mice displayed similar parasitemia, and the two groups immunized with the ASP-2 gene showed a decreased parasitemia when compared with the vector control immunized groups." (PMID 29081775, 2017). "We observed reduced accumulation of PbA-PEs in the brain of mice treated with iNO as compared to parasitemia-matched air-breathing mice, and this reduction was accompanied by decreased levels of ICAM-1 expression in the brain." (PMID 22110737, 2011). "In silico analysis showed several of these piRNAs were computationally predicted to target and potentially regulate expression of genes including SMAD2, EGR1, ICAM1, CX3CL1, and CXCR2, which have been implicated in parasite infection, pathogenesis, and various cardiomyopathies." (PMID 36936778, 2023). "Few studies have investigated the expression or presence of ICAM1 during parasite infection." (PMID 36936778, 2023). "Additionally, we investigated ICAM-1-mediated immune responses in rainbow trout challenged with viral, bacterial, and parasitic infections." (PMID 34489953, 2021). "Therefore, our findings provide important insights into the predominant role of ICAM-1 genes in the mucosal immune responses to viral, bacterial, and parasitic infections in teleost fish." (PMID 34489953, 2021). "We compared expression of ICAM1, ICAM2, and VCAM1 proteins in the vasculature of the brain at the first peak of parasitemia in both strains, by ex-vivo microscopy." (PMID 35787830, 2022). "After adjusting for parasitemia, plasma syndecan-1 also correlated with ADMA (r = 0.45, p < 0.001), angiopoietin-2 (r = 0.44, p = 0.002), and ICAM-1 (r = 0.53, p < 0.0001)." (PMID 33963210, 2021). "Parasitemia was significantly correlated with the markers of thrombopoiesis TPO and IL-11 and with ICAM-1." (PMID 32687542, 2020).
parasitemia (continued). "Although they also lack mature B cells, mice with cerebral trypanosomiasis do not survive past the first peak of parasitemia, so the antibody-mediated response is unlikely to play an important role in ICAM1-mediated neuropathology." (PMID 35787830, 2022). "Mean fluorescent intensity of ICAM1, ICAM2, and VCAM in the brain endothelium in non-infected mice and in mice infected with T. congolense 1/148 or IL3000, at the first peak of parasitemia, and respective representative images." (PMID 35787830, 2022). "Finally, ICAM-1 and VCAM-1 expression were not modulated by the parasite infection." (PMID 31068227, 2019).
thrombosis (14 papers, 2011 to 2025). "A positive correlation was identified between ELAM-1 and ICAM-1 and VWF and between VWF and the allele burden and thrombosis." (PMID 35626232, 2022). "In those patients with thrombosis, the levels of ICAM-1 were highly elevated (180 ± 10 ng/mL) compared to those without thrombosis (90 ± 10 ng/mL) and the controls (80 ± 10 ng/mL)." (PMID 35626232, 2022). "Additionally, the ICAM‐1 expression was increased on vascular endothelium in the thrombosis area compared with the normal vascular." (PMID 38576170, 2024). "In summary, our study has revealed several crucial genes, including FOS, ICAM1, CASP3, and HSP90AA1, which likely play pivotal roles in the therapeutic effects of herbal medicine against venous thrombosis." (PMID 41327671, 2025). "We reported that patients with thrombosis have AECA-mediated endothelial activation marked by the expression of adhesion molecules such as ELAM-1, ICAM-1, and VWF." (PMID 35626232, 2022). "We found high ELAM-1 and ICAM-1 as well as high VWF:Ag in patients with thrombosis compared to patients without thrombosis." (PMID 35626232, 2022). "Results of the present study demonstrate that G-CSF supplement on iron loading hearts can recruit neutrophils/monocytes and up-regulate tissue factors, ICAM-1, TNF-alpha, and MCP-1 thus further activating inflammatory processes in the endo-myocardium and induce cardiac thrombosis." (PMID 21496220, 2011).
acute lung injury (13 papers, 2013 to 2025). A condition of lung damage that is characterized by bilateral pulmonary infiltrates (pulmonary edema) rich in neutrophils, and in the absence of clinical heart failure. "Previously we have also shown that eCIRP up-regulates the expression of ICAM-1 and that neutrophil NETosis by ICAM-1+ neutrophils cause acute lung injury." (PMID 35941574, 2022). "A blockade of ICAM-1 by anti-ICAM-1 antibodies attenuated pulmonary barrier damage in a murine model of SEA-mediated acute lung injury." (PMID 30909619, 2019). "Furthermore, the expression of the endothelial adhesion molecule ICAM‐1, which plays a crucial role in the regulation of leukocyte migration, was significantly elevated in the acute lung injury group." (PMID 40539385, 2025). "Besides being a major receptor for HRVs, ICAM-1 is also involved in the transmigration across airway epithelial monolayers of neutrophils and their activation, and in disorders characterized by neutrophil-mediated acute lung injury." (PMID 23663325, 2013). "Interleukin-6, interleukin-8, surfactant protein D, and soluble tumor necrosis factor receptor I/II (sTNFr I/II), as well as ICAM-1 and VWF, have been found to be elevated in patients with acute lung injury, and their levels fluctuate rapidly in response to different ventilation strategies." (PMID 39408067, 2024).
Allergy (13 papers, 2010 to 2023). An allergy is an immune response or reaction to substances that are usually not harmful. "Although the expression of ICAM-1 in normal human liver cells is low, given its role in mediating leukocyte migration, ICAM-1 up-regulation has been associated with chronic inflammation and autoimmune liver diseases, and allergic diseases." (PMID 36572816, 2023). "For adverse effect identification, the MR-PheWAS suggested that increased level of SERPINA1 increased systolic and diastolic blood pressure level; and inhibition of ICAM1 increased the risk of irritability, allergy, and nervous feelings." (PMID 35772218, 2022). "Our results indicate the potential of allergen/ICAM-1-specific antibody conjugates as a topical treatment strategy for allergy and RV infections." (PMID 36769047, 2023). "Adult patients with either cow’s milk, wheat, oat or rye allergies demonstrated increased ICAM1 protein expression in the lamina propria of the gut." (PMID 33804792, 2021). "The major finding of this study is that the novel SEGRA mapracorat inhibits allergy-related chemokine/cytokine release and the expression of ICAM-1 in two ocular cell types, HConEpiC and HConF." (PMID 23878502, 2013). "The anti-inflammatory effects of mapracorat were determined after allergy-related chemokine/cytokine release and ICAM-1 was induced with IL-4 plus TNF-α in HConEpiC." (PMID 23878502, 2013). "The 19p13.2 locus (rs8111930) was previously reported to be associated to inflammatory adhesion process and also influencing soluble ICAM1 (sICAM1) levels and sICAM1 has been reported by multiple studies to be a key regulator of nasal allergic reaction." (PMID 21625490, 2011). "However, using ICAM-1 as an anchor for bispecific antibodies for allergy treatment is a rather new concept." (PMID 36439110, 2022). "Despite the well-documented role of ICAM-1 in AR, the mechanism/s underlying the regulation of ICAM-1 in allergic diseases is still not clear." (PMID 23472126, 2013). "The analysis implicated a number of genes with roles in allergy and inflammation, including pro-inflammatory cytokines (IL1A, IL1B, IL6, IL8 and TNF) and factors involved in immune cell activation and recruitment (SELE, SELL, SELP, ICAM1, CSF2, CSF3, CCL2 and CXCL2)." (PMID 21067579, 2010). "Expression of intercellular adhesion molecule 1 (ICAM-1/CD54), and the presence of eosinophils and neutrophils at the conjunctival and nasal mucosa was detected in the absence of allergy symptoms in these patients." (PMID 36747108, 2023).
bladder cancer (13 papers, 1996 to 2026). "Here, we revealed that although CQ showed an anticancer effect by reducing the migration and proliferation of the analyzed bladder cancer cells, it increased the expression of ICAM-1, a protein whose expression is associated with higher tumorigenic potential." (PMID 41535692, 2026). "The susceptibility of bladder cancers to CVA21 was directly proportional to ICAM-1 expression, with one exception." (PMID 31100962, 2019). "Initially, the expression of ICAM1 in bladder cancer is very low, but after BCG treatment, its expression in cancer cells and soluble ICAM1 in patient urine increased significantly." (PMID 31164632, 2019). "When treated with MC up to 0.5 μg/mL, three of the most susceptible bladder cancer cell lines showed an increase in ICAM-1 expression with no associated cell death." (PMID 31100962, 2019). "Immunohistochemical studies on 57 patients with bladder carcinomas revealed that the expression of ICAM1 was closely associated with an infiltrative histological phenotype and serum ICAM1 levels have been related to tumor presence, grade and size in patients with bladder cancer." (PMID 16780590, 2006). "Indeed, a role for endothelial ICAM-1 on tumor transmigration could be envisioned as ICAM-1 ligation by LFA-1 receptor on bladder carcinoma cells leads to HUVEC cell retraction and transmigration." (PMID 31511625, 2019). "However, in the present study, iCAM-1 expression was reduced in metastatic bladder cancer cells." (PMID 26230496, 2015). "Furthermore, fibrinogen, which may be a determinant of metastatic potential, mediates bladder cancer cell migration through an ICAM1-dependent pathway." (PMID 16780590, 2006). "Expression of KDR has also been demonstrated in tumors of epithelial origin and the best rules in this study imply that the expression level of KDR is consistently lower in relation to ICAM1 and MAP2K6 when there is nodal involvement in bladder cancer." (PMID 16780590, 2006).
Crohn disease (13 papers, 2009 to 2024). A gastrointestinal disorder characterized by chronic inflammation involving all layers of the intestinal wall, noncaseating granulomas affecting the intestinal wall and regional lymph nodes, and transmural fibrosis. "According to our findings, K469E polymorphism of intercellular adhesion molecule 1 gene may probably participate in the pathogenesis of Crohn’s disease in Iran." (PMID 27099667, 2016). "ICAM-1 levels are increased in colon tissue from ulcerative colitis and Crohn’s disease, whereas ICAM-3 is elevated only in Crohn’s disease; in contrast, ICAM-2 levels are unaltered in both diseases." (PMID 38391953, 2024). "In a model of Caco-2 cells infected with Crohn’s Disease-associated E. coli strain LF82, exposure to EcN decreased the amounts of soluble ICAM1, Gro-α and IL-8 compared with cells infected only with strain LF82." (PMID 37630490, 2023). "ICAM1, which is known to be highly expressed in both Crohn’s disease and UC relative to controls, was downregulated in Caco-2 cells exposed to either HMO-fed bifidobacterial strain." (PMID 26303932, 2015). "This higher expression of ICAM-1 resulted in formation of cell aggregates similar to those observed in patients with Crohn's disease." (PMID 20072622, 2010). "Furthermore, rejecting intestines showed increased expression of serum amyloid A, an acute-phase lipoprotein induced during inflammation or infection and has been shown to correlate with ICAM-1 or VCAM in patients with Crohn’s disease." (PMID 35050145, 2021). "Thus, degraded CGN clearly can activate monocytes to express an increased number of ICAM-1 adhesion molecules, therefore being capable of creating the conditions characteristic of Crohn's disease symptomatology, i.e. PBM accumulation and MGC formation." (PMID 20072622, 2010). "Moreover, increased expression levels of ICAM-1 and LFA-3 (CD58) were also detected in monocytes from patients with Crohn's disease." (PMID 20072622, 2010). "However, using pseudo-bulk generation, no statistically significant increase in ICAM-1 expression levels was found in inflamed or non-inflamed samples from Crohn’s disease patients as compared with healthy individuals in both colon and terminal ileum." (PMID 38428588, 2024).
myocarditis (13 papers, 2010 to 2025). Myocarditis is a condition that is characterized by inflammation of the heart muscle (myocardium). "Intercellular adhesion molecule-1 (ICAM-1), on the other hand, is expressed on cardiac myocytes of patients with myocarditis and is associated with chronic inflammation." (PMID 37568452, 2023). "Expression of ICAM-1 and VCAM-1 adhesion molecules on the cardiac (micro)vascular endothelium is upregulated upon infection with myocarditis-associated viruses." (PMID 35805941, 2022). "Further, PTX-treated mice show reduced frequency of splenic and circulating LFA-1+CCR5+ CD8+ T-cells, decreased expression of ICAM-1 on cardiac tissue and less severe myocarditis." (PMID 25789471, 2015). "A review of the relevant literature revealed that ICAM-1 may be related to the repair of damaged myocardium by recruiting endothelial progenitor cells in the late stage of myocarditis." (PMID 40906170, 2025). "Importantly, it has been reported in the literature that ICAM-1 promotes inflammation and that knocking it down reduces the symptoms of myocarditis; however, in this study, MR analysis revealed that ICAM-1 is a protective factor against myocarditis." (PMID 40906170, 2025). "Another study also revealed that Icariin could downregulate the mRNA levels of TNF-α, ICAM-1, IL-2, and IL-6, which attenuates myocardial inflammation." (PMID 36984421, 2023). "Therefore, inhibition of ICAM-1 production and release may be a potential therapeutic strategy for myocarditis." (PMID 37901475, 2023). "The levels of immunologic activation markers, such as intercellular adhesion molecule-1 (ICAM-1), soluble FAS ligands, and T cell activation markers, are increased in patients with myocarditis." (PMID 39529970, 2024). "Despite the presence of myocarditis, macaques in the CART group expressed lower quantities of MCP-1 and ICAM-1 mRNA in myocardial tissue compared to untreated animals." (PMID 21203448, 2010). "Although ICAM1 and IL10RB have anti-inflammatory effects, they exhibit pro-inflammatory effects in a variety of diseases, which may be unfavorable for myocarditis." (PMID 40906170, 2025). "We did not validate the interaction between ETBR and ICAM-1 by immunoprecipitation, and did not detected the expression of ETBR and ICAM-1 in patients with myocarditis." (PMID 37901475, 2023). "However, the role of ICAM-1 in myocarditis has not been clarified." (PMID 37901475, 2023).
pneumonia (13 papers, 2016 to 2025). An acute, acute and chronic, or chronic inflammation focally or diffusely affecting the lung parenchyma, caused by an infection in one or both of the lungs (by bacteria, viruses, fungi, or mycoplasma.). "In our opinion, this is the first study to identify SNPs in antioxidant (SOD1, CAT, GPX1, NOS, HMOX1, and NQO1) and immunological (IL-1α, IL1B, IL6, TNF-α, IL10, LFA-1, CR2, IL17, IL13, DEFB123, SCART1, and ICAM1) genes as potential suspects for pneumonia resistance/susceptibility in Barki ewes." (PMID 40221769, 2025). "We observed E-selectin, MCP-1, ICAM-1, and interferon gamma-induced protein 10 (IP-10) to be most able to differentiate pneumonia from brain injury." (PMID 30283005, 2018). "Reportedly, blood ICAM-1 content may function as a potent biomarker of patients with pneumonia, including pediatric pneumonia." (PMID 32805728, 2020). "Thromboxane A2 production during pneumonia leads to increased endothelial ICAM-1 expression." (PMID 27845343, 2016). "Our results showed that compared with the Control group, the expressions of TLR4, MyD88, NF-κB, and ICAM-1 of the Model group were significantly higher (P < 0.01), indicating that the TLR4/MyD88/NF-κB signaling pathway was activated during the development of MDR PA-induced pneumonia in rats." (PMID 35071595, 2022).
acute kidney injury (12 papers, 2009 to 2025). Sudden and sustained deterioration of the kidney function characterized by decreased glomerular filtration rate, increased serum creatinine or oliguria. "During inflammation, ICAM-1 plays an important role in pathological events associated with inflammatory reactions, including acute renal failure and acute pancreatitis." (PMID 40005317, 2025). "We also quantified expression levels of additional inflammation mediators with a known involvement in acute kidney injury, including the major adhesion molecules ICAM-1 and P-Selectin." (PMID 22911155, 2012). "As for the renal actions, geraniol exhibited protection against cyclosporine A-induced nephrotoxicity via lowering inflammation mediators, including (ICAM-1, IL-18, and NF-κB), protection against methotrexate-induced acute kidney injury via Keap1/Nrf2/HO-1 and MAPK/NF-κB pathways." (PMID 36009287, 2022). "Depleting neutrophils by anti ICAM-1 antibody can protect against RIRI, demonstrating the determinants of neutrophils in acute kidney injury in mice." (PMID 38495888, 2024). "More interestingly, our study demonstrated that kaempferol could not only alleviate COX-2, but also inhibit the production of MCP-1, ICAM-1, and VCAM-1 at 24 h time point in CLP induced acute kidney injury." (PMID 37440431, 2023). "Additionally, we observed that BAI induced decreases in ICAM-1, MCP-1, and IL-1 expression, which was consistent with the decreased apoptosis of BAI-treated HK-2 cells, revealing that inflammatory responses following hypoxia reperfusion aggravate acute renal failure." (PMID 30384801, 2018).